LYL1 (LYL1 basic helix-loop-helix family member)
Diseases named in the same sentence as LYL1 in open-access papers (continued):
Sharing a sentence is not in itself a finding about the gene and the disease.
cancer (11 papers, 2010 to 2024). A tumor composed of atypical neoplastic, often pleomorphic cells that invade other tissues. "Despite not being identified as an independent prognostic factor in UCEC, LYL1 gene amplification is associated with other poor prognostic factors and correlated with upregulation of cancer-related pathways." (PMID 29716549, 2018). "The LYL1 gene, a basic helix-loop-helix transcription factor and a known oncogene in human and mouse cancers, is linked to many cancer-related properties, such as angiogenesis." (PMID 29716549, 2018). "Considering the results presented in this study, added to the fact that LYL1 is a transcription factor, it is plausible that factors, such as mutations or improper regulation, preventing LYL1 degradation or inactivation by the proteasome may have significant role in cancer formation." (PMID 20844761, 2010). "While most published studies address LYL1 in blood cancers or bone marrow, the role of LYL1 in other types of cancer such as PCa is not well understood." (PMID 39668349, 2024). "Among these genes, PICALM (targeted by EP300), DDX6 (targeted by YY1) and LYL1 (targeted by LMO2) are reported on the COSMIC cancer gene list." (PMID 32850701, 2020). "Correlations between LYL1 amplification and increased expression levels of cancer-related genes (MYC, CDK6, PRKACA, and ERBB2) are also observed." (PMID 29716549, 2018). "Specifically, MYC, CDK6, PRKACA, and ERBB2, all well-known oncogenes and cancer markers, were overexpressed in conjunction with LYL1 gene amplification." (PMID 29716549, 2018). "Heightened levels of cancer-related genes expressed in concert with LYL1 amplification were similarly investigated through differentially expressed gene and gene set enrichment analyses." (PMID 29716549, 2018). "As user-defined regions of interest, we selected 10,000 binding sites of LYL1, a transcription factor (TF) associated with hematopoietic cells, and GRHL2, an important pioneer TF for epithelial cells playing a role in a wide variety of cancer types." (PMID 39704700, 2024). "However, the ctDNA in the plasma from patients with cancer altered the balance between DNA from hematopoietic versus epithelial cells visible as decreased amplitudes for LYL1." (PMID 31604930, 2019). "UCEC ranked second among cancers in terms of LYL1 gene amplification." (PMID 29716549, 2018). "Through our TCGA data analysis of LYL1 gene amplification in patients with UCEC, we discovered that overexpressed cancer-related genes are enriched by MAPK, WNT, and cell cycle pathways in such patients." (PMID 29716549, 2018). "Curiously, somatic amplifications of the LYL1 gene frequently accompany UCEC, more so than most other cancers, ranking second among TCGA listings." (PMID 29716549, 2018). "However, we discovered that cancer-related pathways, such as MAPK, WNT, and cell cycle pathways are upregulated in patients with LYL1 amplification." (PMID 29716549, 2018).
hematological diseases (3 papers, 2014 to 2022). "Super-enhancers associated with LYL1 were common to all three hematological diseases (AML, T-ALL, and B-ALL)." (PMID 35842703, 2022). "Compared with the patients with other hematological diseases, the patient had higher levels of LYL1, NOTCH1, PAX5, MYC, and E2B, all of which contribute to the development of T and B cells." (PMID 33126303, 2020). "In line with other limited studies, our work points to the value of LYL1 and presents this transcription factor as a new target for therapeutic inhibition in hematological malignancies." (PMID 25035669, 2014).
bacterial infections (1 paper, 2022). "Considering the minor effects of Lyl1 deletion in adult hematopoiesis, this study aims to evaluate the outcomes of Lyl1 deficiency in the presence of bacterial infections." (PMID 36119114, 2022). "Given the potential host regulative mechanism linked to Lyl1 expression, we next aimed to investigate various intracellular signaling cascades regulating Lyl1 expression in response to agonist stimulation of pattern recognition receptors that are mainly activated by bacterial infections." (PMID 36119114, 2022). "However, we demonstrate novel functions of Lyl1 during bacterial infection in both in vitro and in vivo murine models." (PMID 36119114, 2022). "Collectively, this data suggests that the downregulation of Lyl1 may not be a consequence of an immune evasion mechanism caused by Mtb, but rather a host regulatory mechanism to potentially control bacterial infection." (PMID 36119114, 2022).
blood cancers (1 paper, 2024). "Most of the studies analyzing LYL1 function were performed in different types of blood cancer including AML." (PMID 39668349, 2024).
hematological cancer (1 paper, 2022). "Analysis by LC-MS/MS identified more than 600 Lmo2-interacting molecules in physiological LPs, including the previously reported components of Lmo2 complexes in hematological cancer cell lines, Lyl1, Tal1, Ldb1, Tcf12, Tcf3, and Cbfa2t3 (also known as ETO2 or MTG16)." (PMID 36126774, 2022).
infection (1 paper, 2022). The state of being infected such as from the introduction of a foreign agent such as serum, vaccine, antigenic substance or organism. "Overall, increased bacterial burdens and exacerbated inflammation in the site of infection can drive susceptibility, yielding Lyl1-/- mice to succumb to the Mtb infection." (PMID 36119114, 2022). "Lyl1-deficient mice show reduced survival to Mtb HN878 infection with increased bacterial burden and exacerbated inflammatory responses in chronic stages." (PMID 36119114, 2022). "A medium dose of hypervirulent Mtb HN878 infection caused Lyl1-/- mice to succumb to infection as early as 12-weeks post-infection compared to 24-weeks for WT mice." (PMID 36119114, 2022). "With the increased mycobacterial burden in the lungs of Lyl1-/- mice, increased pathology, and inflammation, especially at the chronic stage of 10-weeks post-infection were observed." (PMID 36119114, 2022). "However, the loss of Lyl1 does indeed induce neutrophil and monocyte recruitment to the site of infection, as well as excessive neutrophil chemo-attractant secretion, which could potentially be compromising the immune system for the exaggerated inflammation and effective eradication of Mtb HN878." (PMID 36119114, 2022). "At 10-weeks post-infection, Lyl1-/- lungs reveal decreased IFN-γ with increased IL-1 levels in comparison to WT lungs." (PMID 36119114, 2022). "However; our findings warrant further research into cell specific or inducible Lyl1 knockout mouse models to delineate the role of the intriguing transcription factor in infection disease models." (PMID 36119114, 2022). "The strong phenotype was translated to increased mycobacterial burden in Lyl1-deficient lung and spleen accompanied by increased organ weight index at chronic stages of 6- and 10-weeks post-infection but not earlier stages of 3-weeks post-infection." (PMID 36119114, 2022). "Furthermore, Lyl1-/- lungs exhibited reduced GM-CSF levels at both 6- and 10-weeks post-Mtb HN878 infection." (PMID 36119114, 2022). "Moreover, the secretion of neutrophil chemoattractants, CXCL1 and CXCL5, were significantly induced after 6- and 10-weeks post-infection in the absence of Lyl1." (PMID 36119114, 2022).
LYL1 also shares sentences with these, for which no sentence is quoted: prostate carcinoma (2 papers); erythroleukemia (1); glioma (1); gliosarcoma (1); heart disease (1); Immunodeficiency (1); Lymphadenopathy (1); schizophrenia (1); Splenomegaly (1); thymic lymphomas (1).